GGTLC1 (gamma-glutamyltransferase light chain 1)
Synonyms: GGTLA4; dJ831C21.2; dJ831C21.1; GGTL6; GGTLA3
Tractability: No criterion of Open Targets' tractability assessment is met for any kind of drug.
Gene: Protein-coding gene on chromosome 20 (23,985,050 to 23,988,779, reverse strand). Ensembl gene ENSG00000149435.
Gene Ontology:
Molecular function: protein binding; glutathione hydrolase activity
Biological process: leukotriene D4 biosynthetic process; glutathione catabolic process
Genetic constraint (gnomAD): Loss-of-function variants: 14 observed, 19.65 expected, observed/expected ratio (o/e) 0.71, 90% interval 0.47 to 1.11. The upper end of that interval is the gene's LOEUF score, 1.11, which puts it in group 4 of 6, group 1 being the genes least tolerant of losing a copy. Missense variants: 304 observed, 315.45 expected, observed/expected ratio (o/e) 0.96, 90% interval 0.88 to 1.06. Synonymous variants: 110 observed, 127.52 expected, observed/expected ratio (o/e) 0.86, 90% interval 0.74 to 1.01.
Homologues: Orthologues: chimpanzee GGTLC1 (99% identical), macaque GGT1 (92% identical), dog GGT1 (84% identical), rat Ggt1 (79% identical), mouse Ggt1 (77% identical), zebrafish ggt1a (63% identical), zebrafish ggt1b (57% identical), zebrafish ggt1l2.2 (44% identical), Drosophila melanogaster Ggt-1 (44% identical), zebrafish ggt1l2.1 (43% identical), zebrafish si:dkey-222h21.12 (43% identical), zebrafish si:ch73-236c18.3 (42% identical), and 3 more. Paralogues in human: GGT1 (96% identical), GGTLC3 (89% identical), GGTLC2 (86% identical), GGT5 (40% identical), GGT7 (28% identical), GGT6 (15% identical).
Diseases named in the same sentence as GGTLC1 in open-access papers:
GGTLC1 is named in the same sentence as 177 diseases in open-access papers, as found by Europe PMC text mining. Sharing a sentence is not in itself a finding about the gene and the disease. The quoted sentences say what the papers report.
breast carcinoma (3 papers, 2022 to 2025). "Through functional enrichment analysis, immune microenvironment analysis, and other computational analysis methods, we identified PRC1, GGTLC1, and IRS1 as genes that may mediate breast cancer chemoresistance through the immune pathway." (PMID 35387129, 2022). "Through the random walk method, we finally identified that GGTLC1, PRC1, and IRS1 may have produced breast cancer drug-resistant phenotypes through immune-mediated pathways." (PMID 35387129, 2022). "We discovered three genes: PRC1, GGTLC1, and IRS1 that may mediate breast cancer chemotherapy resistance through immune pathways and found that immune regulation disorders may be some of the key factors in the survival of breast cancer patients." (PMID 35387129, 2022).
endometrial cancer (2 papers, 2025). Primary or metastatic malignant neoplasm involving the endometrium (mucous membrane that lines the endometrial cavity). "A study finds GGTLC1 upregulated in endometrial cancer, inhibiting its progression by regulating the TGF-β/Smad pathway, a potential target for treatment." (PMID 40836945, 2025).
prostate carcinoma (1 paper, 2025). A carcinoma that arises from epithelial cells of the prostate gland. "Our results showed that GGT1/5/6/7 genes are the predominant isoforms while GGTLC1/2/3 is expressed at a very low level in prostate tissues, although there are some outliers with higher levels of GGTLC2 in primary prostate cancers." (PMID 40094020, 2025).
renal clear cell carcinoma (1 paper, 2025). "Therefore, our study initially focused on the relationship between GGTLC1 expression and clinicopathological features in patients with renal clear cell carcinoma, but the study of the molecular mechanism of GGTLC1 in renal clear cell carcinoma cells still needs further in-depth analysis." (PMID 40836945, 2025).
tumor (40 papers, 2010 to 2025). "First, we examined the expression levels of GGTLC1 in normal and tumor tissues paired with the TCGA database and found that GGTLC1 was highly expressed in normal samples." (PMID 40836945, 2025). "In addition, GGTLC1 was also closely related to oxidative stress, ROS production, and tumor cell proliferation." (PMID 35387129, 2022). "Finally, we compared the protein expression levels of GGTLC1 in normal and tumor tissues." (PMID 40836945, 2025). "However, the relationship between GGT1, GGTLC1, and the IME of KIRC and the mechanisms leading to tumor heterogeneity have not been fully investigated." (PMID 40836945, 2025).
cancer (13 papers, 2017 to 2025). A tumor composed of atypical neoplastic, often pleomorphic cells that invade other tissues. "Similarly, we examined cancer and paracancer samples from four KIRC patients in Dalian Central Hospital, which all showed low protein expression levels of GGTLC1 in tumors." (PMID 40836945, 2025).
GGTLC1 also shares sentences with these, for which no sentence is quoted: liver fibrosis (24 papers); diabetes (19); fatty liver disease (18); Hypertension (18); Cirrhosis (17); Insulin resistance (17); cholestasis (16); hepatocellular carcinoma (14); liver disease (14); Hepatic steatosis (11); metabolic syndrome (10); chronic hepatitis B (8); biliary atresia (7); nonalcoholic fatty liver disease (7); type 2 diabetes (7); cardiovascular disease (6); fibrosis (6); infection (6); Obesity (6); Hyperbilirubinemia (5); Stroke (5); atherosclerosis (4); End Stage Liver Disease (4); Hepatitis (4); Hypoalbuminemia (4); liver cirrhosis (4); liver dysfunction (4); neutropenia (4); Thrombocytopenia (4); cholangitis (3).
A further 141 diseases each share a sentence with GGTLC1 in 3 papers or fewer.